CCR7 (C-C motif chemokine receptor 7)
Diseases named in the same sentence as CCR7 in open-access papers (continued):
Sharing a sentence is not in itself a finding about the gene and the disease.
Cirrhosis (4 papers, 2015 to 2025). A chronic disorder of the liver in which liver tissue becomes scarred and is partially replaced by regenerative nodules and fibrotic tissue resulting in loss of liver function. "Additionally, anoikis-related genes such as ACTG1, STAT1, and CCR7 have been identified as biomarkers for cirrhosis, providing insights into the disease’s immune landscape and potential for targeted therapies." (PMID 41223189, 2025). "To examine B cell phenotypes in D-LC caused by HBV, we performed flow cytometry using a panel of 11 markers (CD19, CD10, CD38, IgD, CD21, CD27, CCR7, CXCR3, CXCR4, CXCR5, and IL-21R) and demonstrated the changes of B cell subsets for the first time in HBV-associated advanced cirrhosis." (PMID 34248941, 2021). "The expression of CD32, TLR4, and CXCR4 was increased in cirrhosis, whereas the expression of IFNAR, CD206, CCR5, and CCR7 was reduced." (PMID 37004869, 2023). "The frequencies of ICOS+ and CCR7+ CXCR5+CD45RA−CD4+ T cells were higher in HCC patients than in HC (P = 0.002 and P < 0.001, respectively), and the percentage of ICOS+ Tfh cells was correlated with the incidence of cirrhosis in HCC patients (P = 0.039)." (PMID 26517519, 2015). "CXCR4 (AUC = 0.941), COL1A2 (AUC = 0.919), CCR7 (AUC = 0.878), COL1A1 (AUC = 0.853), CXCL12 (AUC = 0.848), and CXCL8 (AUC = 0.828) had similar AUC values, demonstrating that the identified hub genes exhibited a reliable discriminatory capacity as potential biomarkers for cirrhosis." (PMID 41223189, 2025).
diffuse large B-cell lymphoma (4 papers, 2021 to 2025). "Higher expression of CCR7 is also associated with worse prognosis in diffuse large B-cell lymphoma." (PMID 35123499, 2022). "The prognostic significance of the chemokine receptor CCR7 in diffuse large B-cell lymphoma (DLBCL) has been reported previously." (PMID 39735670, 2025). "Nonetheless, in other blood cancers such as diffuse large B-cell lymphoma (DLBCL) or T cell prolymphocytic leukemia (T-PLL) a clear correlation was found between CCR7 expression levels at diagnosis and OS." (PMID 33841445, 2021).
endometrial cancer (4 papers, 2016 to 2024). Primary or metastatic malignant neoplasm involving the endometrium (mucous membrane that lines the endometrial cavity). "Eight IRGs were incorporated to construct a nomogram for survival prediction in endometrial carcinoma patients, including CCR7, GNA15, GPR132, LTA, MYC, NOD2, P2RX4 and P2RY2." (PMID 36207698, 2022). "By contrast, we recently found that CD103+ TIL in endometrial cancer were of a CD45RA-CD45RO+CCR7+/− phenotype." (PMID 27650547, 2016). "In other panels, CD25++ CD45RA+CD4+ T cell, CD28- CD8+ T cell, CCR7 on naive CD8+ T cell, myeloid Dendritic Cell, Natural Killer cell, Basophil cell had positive links with endometrial cancer." (PMID 38746677, 2024). "Among these genes, CCR7, MYC and NOD2 have been reported in a large number of tumor studies, including endometrial cancer, while P2RX4, GNA15, and GPR132 genes have few molecular biological experiments to verify their role in endometrial cancer progress." (PMID 36207698, 2022).
fatty liver (4 papers, 2016 to 2023). "Recent studies also showed that CCR7(-/-) mice were protected from fatty liver and dyslipidemia and exhibited increased thermogenesis on high-fat feeding." (PMID 30884843, 2019). "The absence of CCR7 decreases IL-10-producing iNKT cells in fatty liver, and exacerbates NAFLD." (PMID 33853536, 2021). "CCR7 deficiency did not impact HFD‐induced weight gain, hepatic steatosis, or glucose intolerance." (PMID 27655794, 2016).
gastric tumors (4 papers, 2017 to 2022). "The results showed that upregulation of CCR7 magnificently lowered the OS of esophageal and gastric tumors patients." (PMID 35874608, 2022). "Clearly, CCR7 has distinct effects in different gastric tumors." (PMID 35203305, 2022).
graft versus host disease (4 papers, 2016 to 2025). An immune system disorder that occurs after allogeneic hematopoietic stem cell transplant and is a reaction of donor immune cells against host tissues. "Previous studies demonstrated that CCR7-modified mesenchymal stem cells (MSCs) enhance the homing efficiency of transferred cells into LNs and attenuate the immune response during graft-versus-host disease." (PMID 40309773, 2025). "TSCM cells, featured by CD45RA+ CD45RO− CD27+ CD28+ CCR7+ CD62L+ CD95+ CD122+ CD127+, were first discovered in mouse models of human graft versus host disease (GVHD) in 2005 and isolated in vitro in 2013." (PMID 38049832, 2023).
liver cancer (4 papers, 2022 to 2025). An epithelial or non-epithelial malignant neoplasm that arises from the liver. "The CCR7/CCL21 transport system involved in intrahepatic lymphocyte transport, as elucidated in our study, may be strongly associated with lymphatic and intrahepatic metastasis of malignant liver tumors." (PMID 40038879, 2025).
malaria (4 papers, 2015 to 2025). Malaria is a serious and sometimes fatal disease caused by a parasite that commonly infects a certain type of mosquito which feeds on humans. "Children with uncomplicated malaria and 4-week recovery had elevated levels of TEMRA CD4+CD45RA+CCR7− versus community controls (1.8% vs 0.7% and 1.6% vs 0.7%, respectively)." (PMID 41285032, 2025). "Moreover, in an independent experiment (n = 10 Malian children) T-bethi B cells of malaria-exposed children expressed markers that are known to be associated with atypical MBCs, with higher surface expression of FCRL5, CD11c, CXCR3 and CD95, and decreased expression of CD35, CD40, CXCR5 and CCR7." (PMID 28953967, 2017).
mantle cell lymphoma (4 papers, 2010 to 2023). Mantle cell lymphoma is a rare form of malignant non-Hodgkin lymphoma affecting B lymphocytes in the lymph nodes in a region called the ``mantle zone''. "The present study aimed to evaluate the in vivo therapeutic efficacy of an anti-CCR7 antibody in a xenografted human mantle cell lymphoma model." (PMID 24305507, 2013). "Indeed, results from our laboratory have demonstrated that CCR7 plays a major role in the migration and nodular dissemination of certain lymphoproliferative syndromes including chronic lymphocytic leukemia (CLL) and mantle cell lymphoma (MCL)." (PMID 24305507, 2013).
metastatic melanoma (4 papers, 2018 to 2025). A melanoma that has spread from its primary site to another anatomic site. "Treatment of metastatic melanoma-derived cell lines with histone deacetylase inhibitor and demethylating agents demonstrated that this increase in CCR7 expression is associated with the enhanced migratory responses to CCL21 stimulation." (PMID 30420855, 2018). "Multiplex immunofluorescence staining of sentinel lymph node tissues from metastatic melanoma patients confirmed protein-level co-expression of IRF4 with IRF8 in CD11C + CCR7+ mregDCs." (PMID 40890106, 2025). "CCR7 has also been found on circulating tumor cells and human metastatic melanoma cell lines." (PMID 30420855, 2018). "Effector memory (em) T cells were gated as CD45RO+CCR7+CD27−CD57− cells, which were previously found to be expanded intratumorally in metastatic melanoma patients responding to anti-PD1 therapy." (PMID 36672279, 2023).
mycosis fungoides (4 papers, 2020 to 2025). Classical mycosis fungoides is the most common type of mycosis fungoides (MF), a form of cutaneous T-cell lymphoma, and is characterized by slow progression from patches to more infiltrated plaques and eventually to tumors. "Elevated CCR7 presence was also found on the membrane of MyLa cells derived from a patient with mycosis fungoides that showed migration to CCL21 mediated via the mTOR pathway." (PMID 35203305, 2022).
Sézary syndrome (4 papers, 2018 to 2024). "Expression of several chemokine receptors was elevated in cutaneous T-cell lymphoma, primarily Sézary syndrome samples, which included CCR7." (PMID 35203305, 2022).
Sjögren's syndrome (4 papers, 2007 to 2026). "Although we previously reported autoimmune exocrinopathy resembling Sjögren's syndrome (SS) in the lacrimal and salivary glands from C-C chemokine receptor 7 (CCR7)-deficient mice, it is still unclear whether CCR7 signaling might specifically affect the dynamics and functions of Treg cells in vivo." (PMID 20052419, 2010). "Previously we reported that autoimmune exocrinopathy resembling Sjögren's syndrome (SS) developed in CCR7−/− mice." (PMID 20052419, 2010). "Finally, confocal analysis showed that CCR7+Treg cells were detectable in normal salivary glands while the number of CCR7+Treg cells was extremely decreased in the tissues from patients with Sjögren's syndrome." (PMID 20052419, 2010). "In Sjögren’s syndrome, the expression of CCL19/CCR7 is significantly elevated in salivary gland tissue." (PMID 41481752, 2026). "Recently, an increased frequency of CCR7+CD4+ T cells, which was shown to be closely correlated with EULAR Sjögren's syndrome disease activity index (ESSDAI), was found in pSS patients, suggesting that CCR7 might participate in the development of pSS by mediating the migration of CD4+ cells." (PMID 31068931, 2019).
triple-negative breast carcinoma (4 papers, 2020 to 2026). An invasive breast carcinoma which is negative for expression of estrogen receptor (ER), progesterone receptor (PR), and human epidermal growth factor receptor 2 (HER2). "CCR7 expression in triple-negative breast cancer cells led to reduced anoikis and increased tumor cell survival, with concomitant activation of ERK and Akt signaling." (PMID 35203305, 2022). "Activation of TAK1 was shown to increase expression of CCR7 and enhance lymph node invasion of triple-negative breast cancer cells." (PMID 35203305, 2022). "It was further found that in a murine model of triple negative breast cancer, CCR7 knockout reduced the metastasis of 4T1 cells." (PMID 32253815, 2020). "The results demonstrated that the expression of CCR7 in triple negative breast cancer was related to tumor metastasis." (PMID 32253815, 2020). "Furthermore, when modified antibodies were used to block CCR7 function in the 4T1 mouse model, the concomitant reduction in CCR7 reduced triple-negative breast cancer lymphatic metastasis." (PMID 35203305, 2022). "Additionally, in a mouse model of murine 4T1 triple-negative breast cancer, when CCR7 was knocked down by shRNA, growth and invasive properties were curtailed, suggesting that CCR7 enhances metastasis via promoting tumor cell proliferation/invasion at the metastatic site." (PMID 35203305, 2022). "Using the highly invasive triple-negative breast cancer MDA-231 cell line, it was shown that CCR7 deregulated apoptosis without any ECM interactions both in vitro and in vivo, resulting in increased cell survival." (PMID 35203305, 2022).
type 1 diabetes (4 papers, 2016 to 2023). "Previous studies also indicated that both Ccr7 and Dhps play an important role in the recruitment of T-cells like diabetogenic Th1 cells, into inflamed islets, and thus in the pathogenesis of type 1 diabetes." (PMID 35180880, 2022). "The antigen-specific cells in individuals with type 1 diabetes expressed increased CXCR3 and decreased CCR7, indicating differentiation to Th1-like effector cells." (PMID 32157332, 2020).
adult T-cell leukemia/lymphoma (3 papers, 2011 to 2022). A peripheral (mature) T-cell neoplasm linked to the human T-cell leukemia virus type 1 (HTLV-1), adult T-cell leukemia/lymphoma is endemic in several regions of the world, in particular Japan, the Caribbean, and parts of Central Africa. "Initial investigations in peripheral blood mononuclear cells from patients with adult T-cell leukemia revealed upregulated CCR7 mRNA expression." (PMID 35203305, 2022).
allergic conjunctivitis (3 papers, 2013 to 2021). "Antagonists of CCL21 seem to prevent the development of chronic graft versus host disease or reduced allergic conjunctivitis by blocking CCR7 in mice." (PMID 25254213, 2014).
central nervous system lymphoma (3 papers, 2010 to 2022). "Using primary central nervous system lymphoma tissue, CCR7 was expressed in all 29 samples tested, along with CXCR4 and CXCR5; in each case, chemokine receptor staining was found only in the cytoplasm, with no membrane staining observed." (PMID 35203305, 2022).
chondrosarcoma (3 papers, 2022 to 2024). A malignant cartilaginous matrix-producing mesenchymal neoplasm arising from the bone and soft tissue. "Decreased miR-21-5p levels fuel chondrosarcoma progression by activating the CCR7/STAT3/NF-κB axis, promoting proliferation, migration, and invasion." (PMID 38542153, 2024). "In vitro experiments using SW1353 chondrosarcoma cells showed that CCL21-activated CCR7 induced an EMT phenotype with expression of phospho-ERK, phospho-AKT, Slug and N-cadherin." (PMID 35203305, 2022). "Furthermore, decreased miR-21-5p levels contribute to chondrosarcoma cell proliferation, migration, and invasion through activation of the CCR7/STAT3/NF-κB pathway." (PMID 38542153, 2024).
endometriosis (3 papers, 2016 to 2024). The growth of functional endometrial tissue in anatomic sites outside the uterine body. "•The expression of IL-17 and CCR7 by iNKT cells are related to endometriosis-associated pain symptoms." (PMID 35576870, 2022). "This is consistent with observations that the CCL19/CCR7 axis contributes to the pathogenesis of endometriosis by promoting proliferation and invasion of endometrial stromal cells." (PMID 39385609, 2024). "The number of CD4+ CCR7+ iNKT cells decreased in patients with endometriosis and severe dysmenorrhea compared to patients with mild/absent dysmenorrhea (26.9 ± 31.8 vs. 51.0 ± 21.7; p = 0.022)." (PMID 35576870, 2022). "The number of CD4+ iNKT cells expressing CCR7 (35.6 ± 30.6 vs. 31.6 ± 31.0; p = 0.439) and the number of DN iNKT expressing CCR7 (11.18 ± 15.87 vs. 6.76±14.08; p = 0.801) were similar between the endometriosis and control groups." (PMID 35576870, 2022). "The authors observed a decreased number of CD4+ CCR7+ iNKT cells in patients with endometriosis and severe dysmenorrhea, suggesting that the immune response may play a role in the severity of the disease and its symptoms." (PMID 35576870, 2022). "Patients with endometriosis with severe dysmenorrhea and acyclic pelvic pain had increased production of IL-17 by CD4+ iNKT cells and decreased numbers of CD4+ CCR7+ cells." (PMID 35576870, 2022).
fibrosis (3 papers, 2010 to 2020). the formation of excess fibrous connective tissue in an organ or tissue in a reparative or reactive process. "This deviation for an M2 profile was corroborated by the lower CCR7 expression in lung macrophages from trained mice group with fibrosis, since those macrophages with M1 profile increase the CCR7 expression, as evidenced in trained mice group without fibrosis." (PMID 33123311, 2020). "CCR2 and CCR7 are proved to be expressed on HSCs and involved in cell migration, extracellular signal transduction, wound healing and fibrogenic responses in fibrosis models." (PMID 22905138, 2012). "These histologic differences were confirmed by the quantification of hydroxyproline, an index of total lung collagen and fibrosis: on day 21 after BLM injection, the lungs of CCR7-/- mice had significantly less collagen-associated hydroxyproline compared with those of WT mice." (PMID 20815874, 2010).
gallbladder cancer (3 papers, 2016 to 2024). "Hong demonstrated that CCR7 mediated the TNF-α-induced lymphatic metastasis of gallbladder cancer through the “ERK1/2-AP-1” and “JNK-AP-1” pathways." (PMID 39127853, 2024). "The results indicated that CCR7 is overexpressed in gallbladder cancer tissues, and is at low expression in normal tissues." (PMID 27009073, 2016). "In this study, we detected the expression of CCR7 in gallbladder cancer for the first time, and revealed the relationship between CCR7 and the clinicopathological factors of GBC patients." (PMID 27009073, 2016). "In the present study, we used immunohistochemical techniques to investigate the expression of CCR7 in 42 gallbladder cancer specimens and 22 samples of normal gallbladder tissues adjacent to the cancer site." (PMID 27009073, 2016). "Taken together, CCR7 overexpression may be involved in the lymph node metastasis of gallbladder cancer." (PMID 27009073, 2016). "Therefore, we hypothesized that TNF-α might promote lymphatic metastasis of gallbladder cancer via upregulation of CCR7." (PMID 27009073, 2016). "Thus, we speculated that TNF-α might promote lymphatic metastasis of gallbladder cancer through upregulation of CCR7." (PMID 27009073, 2016). "However, the relationship between CCR7 and the lymph node metastasis of gallbladder cancer has not yet been reported." (PMID 27009073, 2016).
HCMV infection (3 papers, 2017 to 2022). "Thus, HCMV is able to not only inhibit upregulation of the respective chemokine receptor CCR7, when infecting iDCs prior to maturation, but also hamper migration toward CCL19 beyond CCR7-targeting, via the induction of adhesion upon HCMV infection of mDCs." (PMID 28484459, 2017). "Considering the time course of infection, the expression of CD27 and CD28 was progressively lost after HCMV infection to reach a stable CD27-/CD28-, CCR7-, CD45RA+, CD8+ TEMRA phenotype during chronic infection such as in HV hosts with a latent HCMV infection." (PMID 36532017, 2022). "After a primary HCMV infection or a reactivation, the homeostasis of overall circulating CD8T cells subsets changes toward a decrease in naive CD8T cells counterbalanced by an increase in effector CCR7- memory T cells re-expressing CD45RA (TEMRA) cells." (PMID 36532017, 2022). "We show a differential regulation of CCR7 and CXCR4 upon HCMV infection of mDCs." (PMID 28484459, 2017).
ileitis (3 papers, 2016 to 2021). "ΔARE/CCR7−/− mice also develop exacerbated ileitis and multiorgan inflammation." (PMID 32244928, 2020). "This shift from naïve (CCR7hiRO-) to chronically activated (CCR7-RO-) CD8+ T cells in the blood of CD patients predicts the previously reported infiltration of activated CD8+ T cells into small bowel lesions of both ileitis-prone mice and human CD patients." (PMID 27669154, 2016).
inflammatory bowel disease (3 papers, 2012 to 2025). A spectrum of small and large bowel inflammatory diseases of unknown etiology. "In inflammatory bowel disease, blockage of CCR7 has been suggested as a target for treatment." (PMID 31614573, 2019).
laryngeal squamous cell carcinoma (3 papers, 2019 to 2025). A squamous cell carcinoma that arises from the larynx. "The chemokine receptors CCR6 and CCR7 have been reported to be involved in the presence of Foxp3+ Treg cell in favor of progression of laryngeal squamous cell carcinoma." (PMID 30216450, 2019). "A study on laryngeal squamous cell carcinoma has shown that chemokine receptors CCR6/CCR7 and their ligands CCL19/CCL20 synergically drive cervical lymph node metastasis of laryngeal squamous cell carcinoma through differential expression and Treg recruitment." (PMID 41445742, 2025).
malnutrition (3 papers, 2017 to 2026). Inadequate nutrition resulting from poor diet, malabsorption, or abnormal nutrient distribution. "T-cell sensitivity to glucocorticoids was required for elevated expression of CXCR4 and CCR7 in naïve CD4+ T cells during malnutrition." (PMID 41992943, 2026). "Finally, the expression of Ccr7, a chemokine receptor involved in SP thymocyte migration towards the medulla, was significantly upregulated due to malnutrition (p < 0.001)." (PMID 28397794, 2017). "Because PGE2 induces CC chemokine receptor 7 (CCR7) expression and CCR7 has a critical role in the migration of myeloid cells from the skin to draining LN, we evaluated the effect of malnutrition and PGE2 on CCR7 receptor expression and its role in cell trafficking from skin to spleen." (PMID 36630476, 2023).